KRT14 (keratin 14)
Diseases named in the same sentence as KRT14 in open-access papers (continued):
Sharing a sentence is not in itself a finding about the gene and the disease.
cancer (161 papers, 2008 to 2026). A tumor composed of atypical neoplastic, often pleomorphic cells that invade other tissues. "Cancer-associated fibroblasts were shown to exert a powerful stimulatory effect on the expression of KRT14, which is a basal/myoepithelial marker." (PMID 36949761, 2023). "Several studies have reported that high KRT14 expression can cause poor prognosis in cancers." (PMID 37169018, 2023). "The underlying correlation between KRT14 and pan-cancer needs to be analyzed further." (PMID 37169018, 2023). "Additional mRNAs, involved in EMT and target of FMRP in cancer cells, such as Microtubule Associated Protein 1B (Mtap1b), Caveolin 2 (Cav2), Desmoplakin (Dsp), Keratin 14 (Krt14), Microphthalmia-Associated Transcription Factor (Mitf) were similarly regulated at the level of translation." (PMID 24092663, 2013). "Notably, FGF7p treatment completely blocked ectopic lumenal KRT14 expression, which could translate into lowered cancer risk if patients received the peptide." (PMID 35748317, 2022). "YAP has been shown to interact with β-catenin in KRT14+ cells and to induce and sustain cancer stem cell survival, EMT, and overall TNBC progression." (PMID 40936697, 2025). "In UC, SOX2 expression is suggested to be a marker for a subpopulation of cancer stem cell (CSCs) that co-express keratin 14 (KRT14) and CD44v6, and these CSCs are responsible for the maintenance, invasion, and progression of UC tumors." (PMID 40643470, 2025). "We investigated the single nucleotide variations (SNVs) of HFRS genes in different cancers and observed that some genes (CCT6A, TF, KRT14, P4HA2, PGK1, SLC16A2, and STC2) were frequently mutated in COAD, STAD, UCEC, and SKCM." (PMID 36998462, 2023). "The structure of clusters was also stabilized by the expression of basal epithelial genes as intercellular adhesion molecule cytokeratin-14 (CK-14) and tumor protein P63 contributed to the collective invasion of polyclonal cancer cells." (PMID 36292996, 2022). "3-Methylcholanthrene (MCA)-induced cSCC in Flii overexpressing mice showed increased markers of cancer metastasis including talin and keratin-14 and a significant increase in SOX9 alongside a reduction in Flii associated protein (Flap-1)." (PMID 34948000, 2021). "The expression of Krt14, however, was observed only in the basal layer of control organoids but detected in the inner suprabasal layers of cancer organoids." (PMID 34785704, 2021). "In cancers, KRT14 expressing cells increase with successive rounds of chemotherapy and contribute to the chemoresistance of the tumors." (PMID 32822399, 2020). "We also detected enrichment for transcripts encoding fibroblast-specific protein 1 (FSP1/S100a4), keratins Krt7, Krt8, Krt14 and Krt18 and claudins Cldn3, Cldn4 and Cldn7 in this cluster which were also enriched in epithelial/cancer cells." (PMID 32455670, 2020). "We also observed invasion by KRT14-expressing cancer cells on a collagen I matrix, which was in agreement with previous data." (PMID 31443478, 2019). "Cytokeratin-14 (K14) marks a subpopulation of highly migratory carcinoma cells that are capable of initiating collective invasion, a critical step in metastatic progression of malignant mammary tumours." (PMID 31324807, 2019). "In the current study, one cell expressing KRT14 was found among SOX2-positive cancer cells in the E-side." (PMID 29079795, 2017). "The Human Cancer PathwayFinder PCR Array detected significantly increased expression of KRT14 (keratin 14)." (PMID 29207620, 2017). "Correspondingly, KRT14-positive cells may mediate collective invasion both via cancer cell-intrinsic and stromal-dependent mechanisms." (PMID 38597967, 2024). "The ability of PALB2-mutated cells and spheroids to agglomerate could also protect them against the KRT14 KD, since cluster formation can considerably increase cancer cell survival." (PMID 38597967, 2024). "Gastrokine 1 cooperated with keratin 14, inhibited anoikis, and promoted cancer metastasis." (PMID 36230714, 2022).
cancer (continued). "Indeed, we found that overexpression of CDCP1 in MDCK cysts induced the expression of cytokeratin 14, a promising marker of collective invasion of cancer cells, suggesting a potential role of up-regulation of the CDCP1-Src axis in this process." (PMID 33574034, 2021). "The basal cell marker Krt14 was widely expressed in both control and cancer organoids." (PMID 34785704, 2021). "However, the HPV16 gene transcription mechanisms based on the Krt14 gene promoter differ from those observed in cancer patients and this limitation should be kept in mind when interpreting the gene expression results." (PMID 34684173, 2021). "Perilipin 2 (PLIN2) and sterol O-acyltransferase 1 (SOAT1) are two proteins used to identify sebaceous glands in tissue sections while keratin 14 (KRT14) is useful for outlining the gland when investigating its involvement in cancer or for structural abnormalities." (PMID 30372477, 2018). "Coexpression of keratin 14, a basal cell marker of squamous and glandular epithelia, keratin 5 and involucrin are reported to represent a stem cell or progenitor cell phenotype in cancer cells." (PMID 26807202, 2015). "To establish a role for MCs in conferring local immunosuppression or promoting local pathology in HPV transformed epithelium, we therefore studied a mouse which expresses HPV16 E7, the single HPV early gene most relevant to cervical epithelial progression to cancer, from a keratin 14 promoter." (PMID 25340820, 2014). "Bipotent precursor cells present in mammary stem/progenitor cells and breast TICs/cancer stem cells have been characterized by coexpression of luminal epithelial cytokeratin 18 (K18)/K8 markers and myoepithelial cytokeratin 14 (K14)/α-smooth muscle actin (SMA) markers." (PMID 23300950, 2013). "In addition, fibroblasts (n = 1 068) were identified by COL1A1 and FAP, endothelial cells (n = 2 561) were positive for RAMP2 and CLDN5 expression, smooth muscle cells (n = 1 100) were defined by TAGLN and CNN1, and epithelial/cancer cells (n = 319) were labeled by KRT14 and KRT17." (PMID 40360503, 2025). "The upregulation of multiple lineage plasticity genes, including basal (Trp63, Krt5 and Krt14), metastasis (Snai2, Tgfb1 and L1cam), and stemness (Sox2, Mecom and Sox6) markers was induced by LKB1 loss, further supporting the enhanced cancer cell state plasticity by LKB1 loss." (PMID 39743630, 2025). "Stromal cells (or cancer-associated cells) included endothelial cells (PECAM1/CD31+ and MMRN1+), fibroblasts (COL6A1+, COL1A1+, THY1+, and DCN+), epithelial cells (LAMC2+, KRT5+, and KRT14+), and unassigned name cells (high heat shock proteins expression), suggesting that they were cancerous cells." (PMID 35742914, 2022). "Meanwhile, a large number of BOT carcinomas confined to Von Ebner’s gland of circumvallate papillae were still found in HPV16-transgenic mice where the expression of all the HPV16 early genes is targeted to keratinizing squamous epithelia by the cytokeratin 14 (Krt14) gene promoter." (PMID 36465343, 2022). "Four proteins (KRT14, Hornerin [HRNR], Cell Division Cycle Associated 8 [CDCA8], and Fibronectin Type III Domain Containing 3B [FNDC3B]) were identified as unique to all patient HGSC cells at the cancer–mesothelial interface following this high-stringency approach." (PMID 31443478, 2019). "The heat map shows positive correlation between GJB2 and the five genes (GJB6, KRT6A, KRT6B, KRT14, and IVL) in pan-cancer." (PMID 37427102, 2023). "Single cell sequencing analysis discovered Keratin 14 (KRT14, one of the seven anoikis-related genes) was mainly expressed in malignant cells in various cancers." (PMID 37169018, 2023). "Recently, altered expression of several keratins including keratin 6 (KRT6), KRT14, KRT15, KRT16, KRT17 and KRT19 were reported to coordinate tumorigenesis in different types of cancers." (PMID 35706019, 2022).
cancer (continued). "For example, KRT5, KRT14, and KRT17 overexpression are related to poor survival across different types of cancers, especially breast cancers." (PMID 33441834, 2021). "Our finding that the expression levels of KRT-14, SOX2, CD44, and ALDH1a decreased upon si-m/hVDAC1-B BC treatment suggests that the metabolic reprogramming of cancer cells via VDAC1 depletion reduces CSC markers, suggesting the inhibition of their proliferation and/or induction of differentiation." (PMID 38607066, 2024). "We observed solid ductal carcinoma and SR histologies, including papillary, lobular, and adenosquamous, with high expression of the basal marker KRT14; and all were ER, PR, and HER2 negative." (PMID 37704631, 2023). "Similarly, S100A2, KRT14, KRT17, and KRT6A were overwhelmingly expressed in cancer cells and their expression values were significantly higher than the other cells (log10FC > 3 and P < 0.001)." (PMID 34326696, 2021). "Such classification is achieved based on genomic and transcriptomic analyses, which point to differential expression of specific markers among tumors: the basal cytokeratins KRT5/KRT6A and KRT14, as hallmarks of basal BlCa, and the luminal markers FOXA1 and GATA3, as hallmarks of luminal cancer." (PMID 32758253, 2020). "Moreover, this “class 2” subtype highly expressed KRT14 and genetic signatures related to late cell cycle, cancer stem cell phenotype and EMT, which was in accord with another report that found high CK14/KRT14 to be a determinant of poor NMIBC prognosis." (PMID 32391279, 2020). "Based on cell surface marker profiles and KRT14/KRT19 expression patterns in sh-UNC5A cells, we propose that the gradual loss of UNC5A results in cancer cells acquiring hybrid phenotype without expressing classic markers of EMT." (PMID 29720215, 2018). "Finally, we used immunoFISH to assess KRT14 and HER2 protein levels and HER2 mRNA expression in formal-fixed, paraffin embedded tissues and showed the remarkable spatial heterogeneity that exists within individual HER2+ cancers." (PMID 29184166, 2017). "For example, although the keratin genes (KRT5, KRT14, and KRT17) were found to interact in cancer genome studies, it was not clear how the cluster affects clinical features for cancer." (PMID 37395630, 2022). "In agreement with RT-PCR data (above), HRNR, KRT14, and CDCA8 were detected in cancer cell lysates but not in the mesothelial cell controls." (PMID 31443478, 2019).
infection (24 papers, 2011 to 2025). The state of being infected such as from the introduction of a foreign agent such as serum, vaccine, antigenic substance or organism. "In NAc homogenates, enrichment analyses identified pathways related to immune modulatory pathways, including various types of infection (e.g., KRT14,16,17; HLA-B) and leukocyte migration (e.g., JAM2; PLCG1)." (PMID 37674018, 2023). "Some up-regulated genes at 21 dpi (e.g., Ltf, Cxcl9, Pglyrp1, Prg2, Cxcl13, Cxcl3, Ccl9, Ccl19, Krt5, Krt14, Krt15, Krt17, and Slpi) were also identified in a previous infection study by using H1N1(PR8)." (PMID 38005876, 2023). "There was an increase of Krt14+ cells in urothelial tissue infected with either wild-type or clbP mutant UTI89 24 hours after infection." (PMID 33630958, 2021). "Analysis of wild-type mice 24 h post infection revealed extensive proliferation throughout the basal and I cell compartments and the number of Krt14-expressing cells dramatically increased compared to uninfected animals." (PMID 31597917, 2019). "Consistent with our qRT-PCR analysis, infection of HDFn cells with ΔNp73β in combination with KLF4 + ΔNp63α led to increased expression of KRT14, KRT5, FLG, and SFN as compared to KLF4 + ΔNp63α with control or control alone." (PMID 31216312, 2019). "Three days after infection of the HDFn cells with ΔNp73-expressing lentivirus, we harvested cells, isolated RNA, and performed qRT-PCR for keratinocyte genes that are markers of the iKC state (KRT14, KRT5, SFN, and FLG)." (PMID 31216312, 2019). "Moreover, confocal microscopy showed that a large number of active Yap1 expression was co-localized with Krt14-positive cells, which confirmed the successful infection of lentivirus transducing active Yap1." (PMID 26695440, 2016). "Genes for epithelial cell markers such as cytokeratins 14, 18 and 19 (KRT14, KRT18, KRT19), E-cadherin (CDH1) and epithelial cell adhesion molecule (EPCAM) showed the highest expression at 0 hpi and decreased post-infection." (PMID 34740333, 2021). "Cells infected with KLF4 + ΔNp63α lentivirus had increased expression of basal keratinocyte genes (e.g. KRT14, ITGA3) and reduced expression of fibroblast genes (e.g. MME, VIM) compared to control infections." (PMID 31216312, 2019). "At 3 h p.i. costaining of keratin 14 and ICP0 revealed infection throughout the basal layer of keratinocytes in the DMSO-treated epidermis." (PMID 22022400, 2011). "In this murine model, the human promoter of the cytokeratin 14 gene Krt14 directs the expression of the HPV16 early genes to the basal layer of squamous epithelia, leading to the spontaneous development of lesions characteristic of infection by this virus in humans." (PMID 41150806, 2025).
adenocarcinoma (18 papers, 2009 to 2025). A common cancer characterized by the presence of malignant glandular cells. "Single cell gene analysis showed that some SCCs positive for KRT14 expressed the adenocarcinoma marker KRT8 as well as the EMT markers VIM, and ZEB2." (PMID 29079795, 2017). "Activated EGFR was reported to induce keratin 5 and keratin 14 expression and was associated with the keratin expression percentages in the immune class, while the non-immune class was mostly composed of adenocarcinomas." (PMID 33971902, 2021). "Then, by staining for squamous epithelium markers (including KRT5, KRT6A, SFN, and KRT14) and columnar epithelium markers (including EPCAM and KRT8), groups 3, 7, and 10 were identified as squamous cancer cells, and groups 5, 6, and 8 were identified as adenocarcinoma cells." (PMID 36052088, 2022). "In addition, epithelial cells of patient #6 consisted of a group of NE cells (cluster 4, expressing ASCL1, CHGA, and CHGB), a group of basal cells (cluster 8, expressing KRT5, KRT14, and KRT15) as well as the remaining ARhigh luminal cells, presenting mixed features of both adenocarcinoma and NEPC." (PMID 33328604, 2020). "Poorly differentiated adenocarcinoma may be nonreactive for PSA, which turned out to be hard to differentiate, but the presence of immunoreactivity for cytokeratin 14 and negative staining for high-molecular-weight cytokeratin were helpful in distinguishing it from BCC." (PMID 23941693, 2013).
bacterial infection (2 papers, 2021 to 2022). "We then examined whether bacterial infection played a role in the full spectrum of changes in the corneas of Krt14-Cre; Relaf/f mice as the mice showed open wounds in the cornea." (PMID 34085926, 2021).
metabolic disease (2 papers, 2016 to 2022). A congenital disorder (due to inherited enzyme abnormality) or acquired (due to failure of a metabolically important organ) disorder resulting from an abnormal metabolic process. "To test the hypothesis that VEGF-C plays a role in the promotion of the metabolic disease, we used K14-VEGF-C mice that overexpress human VEGF-C under control of the keratin-14 promoter in the skin and monitored metabolic parameters over time." (PMID 27511834, 2016).
KRT14 also shares sentences with these, for which no sentence is quoted: oral cancer (6 papers); carcinoma in situ (5); invasive carcinoma (5); epidermolytic ichthyosis (4); periodontitis (4); actinic keratosis (3); breast (3); cyst (3); inflammation (3); mammary adenocarcinoma (3); myoepithelioma (3); pachyonychia congenita (3); skin cancer (3); skin squamous cell carcinoma (3); urothelial cell carcinomas (3); Autoimmunity (2); Barrett esophagus (2); carcinosarcoma (2); Cervical dysplasia (2); colorectal cancer (2); cutaneous melanoma (2); diabetes (2); epidermal cyst (2); genetic disease (2); gynaecomastia (2); Hypertension (2); inflammatory bowel disease (2); Insulin resistance (2); keratoderma (2); leukoplakia (2).
A further 106 diseases each share a sentence with KRT14 in 2 papers or fewer.